USP51 (ubiquitin specific peptidase 51)
Description:
Specifically deubiquitinates 'Lys-14' (H2AK13Ub) and 'Lys-16'(H2AK15Ub) of histone H2A regulating the DNA damage response at double-strand breaks (DSBs). USP51 is recruited to chromatin after DNA damage and regulates the dynamic assembly/disassembly of TP53BP1 and BRCA1. Functions in DNA double-strand break repair also by mediating the deubiquitination and subsequent stabilization of DGCR8, leading to the recruitment of DGCR8 binding partners to double strand breaks such as RNF168 or MDC1. In addition, promotes the deubiquitination and stabilization of the transcriptional repressor ZEB1.
Tractability: PROTAC: ubiquitination databases record sites on it.
Target class: Cysteine protease; Cysteine protease CA clan; Protease; Enzyme; Cysteine protease C19 family
Gene: Protein-coding gene on chromosome X (55,484,616 to 55,489,874, reverse strand). Ensembl gene ENSG00000247746.
Subcellular location: Chromosome
Subcellular location (Human Protein Atlas): Cytosol; Nucleoli fibrillar center
Gene Ontology:
Molecular function: chromatin binding; cysteine-type deubiquitinase activity; histone binding; histone H2A deubiquitinase activity; zinc ion binding
Biological process: DNA damage response; DNA repair-dependent chromatin remodeling; regulation of cell cycle process; regulation of double-strand break repair via homologous recombination; regulation of double-strand break repair via nonhomologous end joining; protein deubiquitination
Cellular component: nucleus; chromosome
Homologues: Orthologues: chimpanzee USP51 (99% identical), macaque USP51 (98% identical), rabbit USP51 (88% identical), pig USP51 (86% identical), rat Usp51 (76% identical), mouse Usp51 (72% identical). Paralogues in human: USP22 (52% identical), USP27X (44% identical), USP32 (19% identical), USP9X (19% identical), USP19 (19% identical), USP33 (19% identical), USP11 (18% identical), USP24 (18% identical), USP15 (18% identical), USP20 (18% identical), USP9Y (18% identical), USP44 (18% identical), and 59 more.
Diseases named in the same sentence as USP51 in open-access papers:
USP51 is named in the same sentence as 10 diseases in open-access papers, as found by Europe PMC text mining. Sharing a sentence is not in itself a finding about the gene and the disease. The quoted sentences say what the papers report.
breast carcinoma (9 papers, 2020 to 2025). "To validate the association between DGCR8 and USP51 in patients with breast cancer, we immunohistochemically stained these two proteins in breast tumors (n = 139) from patients with a long-term (~12 years) follow-up record." (PMID 34188037, 2021). "Furthermore, Kaplan–Meier analysis showed that high levels of DGCR8 (log-rank P = 2 × 10−10) and USP51 (log-rank P = 0.0001) were significantly associated with poor overall survival after surgery in patients with breast cancer." (PMID 34188037, 2021). "USP51 depletion inhibited the invasion of mesenchymal-like breast cancer cells by downregulating ZEB1 protein and mesenchymal marker expression and promoting E-cadherin upregulation." (PMID 39196911, 2024). "USP51 was first shown to act as a cancer promoter by targeting ZEB1 for deubiquitination in breast cancer." (PMID 37422632, 2023). "The stability of ZEB1 maintained by USP43 and USP51 promotes the proliferation and metastasis of colorectal and breast cancer." (PMID 36906615, 2023). "USP51 has been demonstrated as a deubiquitinase of ZEB1 in breast cancer cells, and its catalytic activity is induced by phosphorylation of CDK4/6." (PMID 34575114, 2021). "It is believed that imbalances of USP22, USP27X, and USP51 lead to SAGA-related breast cancer development." (PMID 34575114, 2021). "In a subset of human breast cancer cell lines and patient samples, the status of USP51 is correlated with ZEB1 expression." (PMID 32296027, 2020). "In lung adenocarcinoma and breast cancer, CDK4/6-mediated phosphorylation and activation of USP51 is essential for deubiquitinating and stabilizing ZEB1, thereby promoting cancer metastasis." (PMID 40307228, 2025). "In particular, USP51 deubiquitinates ZEB1’s N-terminal region and minces metastasis and therapy resistance in breast cancer." (PMID 36499447, 2022). "Among DUBs, ubiquitin specific peptidase 51 (USP51) binds to the N-terminal of ZEB1 and increases ZEB1 protein stability in breast cancer cell lines." (PMID 33808323, 2021). "Depletion of USP22, USP51, or USP27X inhibits breast cancer growth partly through downregulation of H2Bub1." (PMID 34575114, 2021). "To further examine the pathological correlations between p-USP51, ZEB1, and CDK4/6 activity, we performed immunohistochemical staining for p-RB, p-USP51, and ZEB1 in 265 cases of human primary breast carcinoma." (PMID 32296027, 2020). "In the present study, we provided evidence that USP51 is a bona fide DUB that targets the ZEB1 protein for deubiquitination and stabilization, which is crucial for the induction of EMT and metastasis in breast cancer." (PMID 32296027, 2020). "Moreover, we found a strong positive correlation between the expression of p-RB (an indicator of CDK4/6 activity), p-USP51 and ZEB1 in metastatic human breast cancer samples." (PMID 32296027, 2020). "Given our observation that USP51 directly binds and deubiquitinates ZEB1, it follows that disrupting the interaction between USP51 and ZEB1 would severely diminish ZEB1 activity and thus the aggressiveness of breast cancer in vitro and in vivo." (PMID 32296027, 2020).
lung carcinoma (4 papers, 2022 to 2024). "In lung cancer patients with cisplatin resistance, the upregulation of USP51 diminishes γH2AX formation and increases checkpoint kinase 1 (CHK1) phosphorylation, thereby ensuring an effective cell cycle." (PMID 38702734, 2024). "Furthermore, we analyzed data from GEO (GSE19804) and found that TWIST1 (213943_at) and USP51 (229278_at) were both highly expressed in lung cancer tissues." (PMID 37422632, 2023). "In the cisplatin-resistant lung cancer cell line A549/DDP, USP51 knockdown significantly induces apoptosis and the ubiquitin-mediated degradation of ZEB1, whereas overexpression of USP51 decreases the cleavage of PARP-1 and caspase-3." (PMID 35454770, 2022). "Additionally, USP51 can interact with ZEB1, and the reduction of USP51 levels increases ZEB1 ubiquitination, significantly lowering cisplatin resistance in lung cancer cells." (PMID 38702734, 2024).
gastric cancer (2 papers, 2024 to 2025). A primary or metastatic malignant neoplasm involving the stomach. "It should be noted that other DUBs (such as USP50, USP51, USP52, JOSD3, and UAF1), which were identified to potentially regulate RBM39 in the biochemical screening, neither have high mRNA expression in gastric cancer tissues nor affect the overall patient survival based on the database analysis." (PMID 39260689, 2024).
triple-negative breast carcinoma (1 paper, 2024). An invasive breast carcinoma which is negative for expression of estrogen receptor (ER), progesterone receptor (PR), and human epidermal growth factor receptor 2 (HER2). "Similarly, in triple-negative breast cancer (TNBC), the stabilization of ABCB1 via USP51-mediated deubiquitination enhances resistance to doxorubicin, while targeting USP51 impairs this resistance." (PMID 39679367, 2024).
tumor (9 papers, 2020 to 2025). "Similar to our observations in in vitro-cultured cells, analysis of lysates from mouse-derived tumors indicated that overexpression of TWIST1 alleviated the decreases in the expression of stemness markers caused by USP51 knockdown in the tumor cells." (PMID 37422632, 2023). "The previous study showed that CDK4/6 inhibition facilitates ubiquitination of ZEB1, a key molecule in tumor metastasis, via suppressing activation of the deubiquitinase USP51." (PMID 38596406, 2024). "As cancer stem cells are a key population of cancer cells that result in tumor progression and recurrence, we determined the impact of USP51 on NSCLC cell stemness." (PMID 37422632, 2023). "The results of loss-of-function studies suggested that USP51 knockdown reduced the expression of stemness markers in NSCLC cells, thereby diminishing the growth and tumor sphere formation of NSCLC cells." (PMID 37422632, 2023). "Furthermore, the tumor sphere formation ability of NSCLC cells was decreased upon USP51 knockdown, as determined by measurement of the tumor sphere diameter." (PMID 37422632, 2023). "Notably, USP7, ATXN3, CSN5, and USP51 participate in tumor immunity within the GC microenvironment." (PMID 39605891, 2024). "It was found that USP51 and constitutively photomorphogenic 9 signalosome subunit 5 promote EMT by stabilizing the expression of ZEB1, leading to increased tumor invasion and metastasis." (PMID 38449391, 2024). "USP51 maintains ZEB1 levels, which activates ACTA2 transcription, triggering the mesenchymal characteristics of GC cells and enhancing tumor metastasis." (PMID 39605891, 2024). "Dramatically decreases in the tumor weight and volume were observed upon USP51 depletion, and increasing TWIST1 expression reversed the effect of USP51 knockdown on decreasing the tumor weight and volume." (PMID 37422632, 2023). "Taken together, our investigation revealed that USP51 promotes the stabilization of the TWIST1 protein by deubiquitinating TWIST1, which enhances the stemness of NSCLC cells, leading to NSCLC tumor proliferation." (PMID 37422632, 2023). "HIF1A upregulates USP51 expression under hypoxic conditions, while USP51 stabilizes HIF1A via deubiquitination, thereby maintaining its activity and supporting the proliferative and migratory capacities of tumor cells." (PMID 39995416, 2025). "Finally, our work calls for the development of small-molecule inhibitors that target USP51’s DUB activity or its interaction with DGCR8; such inhibitors have potential as tumor radiosensitizers." (PMID 34188037, 2021). "Altogether, these findings reveal the non-canonical function of DGCR8 in DSB repair and suggest that radiation treatment may result in therapy-induced tumor radioresistance through ATM- and USP51-mediated activation and upregulation of DGCR8." (PMID 34188037, 2021). "Upon depletion of USP51, TWIST1 is polyubiquitinated and subsequently degraded by the proteasome, resulting in a decrease in NSCLC cell stemness and in vivo inhibition of tumor growth; these finding suggest that USP51 could be a candidate therapeutic target for NSCLC." (PMID 37422632, 2023). "In the absence of USP51, NSCLC cells showed decreased expression of stemness markers and attenuated growth and tumor sphere formation." (PMID 37422632, 2023).
cancer (8 papers, 2019 to 2025). A tumor composed of atypical neoplastic, often pleomorphic cells that invade other tissues. "USP51 is a deubiquitinase implicated in the progression and metastasis of several cancers." (PMID 40371639, 2025). "Therefore, we consider that USP51 is associated with cancer cell stemness and cancer progression in patients with NSCLC." (PMID 37422632, 2023). "We then investigated the effects of USP51 on cancer cell metastasis in a xenograft metastasis model." (PMID 32296027, 2020). "Our findings suggest that USP51-dependent stabilization of Bim by AMPK activation plays a critical role in hispidulin-mediated sensitization of cancer cells to apoptosis induced by TRAIL." (PMID 31817696, 2019). "Collectively, we suggest that USP51-dependent stabilization of Bim by AMPK activation has an important role in hispidulin-mediated sensitization of cancer cells to TRAIL-induced apoptosis." (PMID 31817696, 2019). "Accumulating evidence has demonstrated that USP51 contributes to cancer development." (PMID 37422632, 2023). "Notably, the survival analysis indicated that cancer patients with concomitantly high expression of p-RB, p-USP51, and ZEB1 in their tumors had shorter overall survival than those with low p-RB, p-USP51, and ZEB1 expression." (PMID 32296027, 2020). "We found that the knockdown of USP51 resulted in significantly decreased lung metastasis; however, this effect was attenuated in mice carrying ZEB1-expressing tumors, confirming that the knockdown of USP51 reduces cancer metastasis through the regulation of ZEB1 in vivo." (PMID 32296027, 2020). "We next examined whether USP51 depletion could inhibit cancer cell metastasis through the regulation of ZEB1." (PMID 32296027, 2020). "Several DUBs, including USP10, USP18, USP22, USP43, and USP51 have been identified as key regulators of ZEB1 stability, thereby promoting proliferation, migration and invasion of cancer cells across different malignancies." (PMID 39736693, 2024). "In conclusion, we suggest that hispidulin enhances TRAIL-mediated apoptosis in cancer cells, and the mechanism is that hispidulin induces Bim stabilization through CaMKKβ/AMPK-mediated USP51 expression." (PMID 31817696, 2019). "We also plotted the USP51 protein score versus the DGCR8 protein score for individual patients, which revealed a highly significant correlation (Pearson R2 = 0.52, P < 1 × 10−15), indicating the relevance of the identified regulatory mechanism in human cancer." (PMID 34188037, 2021). "However, whether USP51 is involved in cancer cell stemness has not yet been investigated." (PMID 37422632, 2023).
USP51 also shares sentences with these, for which no sentence is quoted: lung adenocarcinoma (2 papers); non-small cell lung carcinoma (2); breast tumors (1); colon cancer (1).